MYCN (MYCN proto-oncogene, bHLH transcription factor)
Diseases named in the same sentence as MYCN in open-access papers (continued):
Sharing a sentence is not in itself a finding about the gene and the disease.
neuroblastoma (continued). "The International Neuroblastoma Risk Group Staging System (INRGSS) includes MYCN status together with age at diagnosis, histology and grade of tumor differentiation, presence or absence of 11q aberrations and tumor-cell ploidy to perform the actual risk-groups classification used in the clinic." (PMID 30344930, 2018). "A p.A300D missense mutation in the PTCH1 gene was previously reported in human neuroblastoma, suggesting that missense mutations could impair neuroblast differentiation and cooperate in MYCN driven tumor formation." (PMID 29492199, 2018). "Furthermore, Cox proportional-hazards regression analysis shows that, adjusted for age, tumor stage and MYCN amplification, DGscore is the only significant prognostic factor for high-risk neuroblastoma patients (P = 0.008)." (PMID 30012197, 2018). "Following the reasoning in our earlier study on glucocorticoid resistance in T-ALL, we hypothesized that synthetic lethal genes would be identified as MRs that mechanistically regulate the transcriptional signature associated with MYCN-amplified neuroblastoma." (PMID 29880876, 2018). "High-risk neuroblastoma, documented to occur in half of all patients, is typically associated with metastasis to the liver, bone or bone marrow, and aggressive features such as MYCN oncogene amplification, as well as an unfavorable prognosis." (PMID 30027525, 2018). "Similarly, retinoic acid induced suppressor miR-34a, which targets MYCN, inhibits neuroblastoma cell growth and causes cell differentiation and apoptosis." (PMID 30237861, 2018). "Three known risk factors, the presence of a MYCN amplification in the tumor, patient age > 18 months at diagnosis and stage 4 disease according to the International Neuroblastoma Staging System (INSS), significantly correlated with elevated MDM2 expression in tumors." (PMID 29416773, 2018). "Neuroblastoma with poor prognosis have been characterized by a high-risk functional MYCN signature." (PMID 29515779, 2018). "However, certain high-risk cohorts, such as patients with MYCN-amplified neuroblastoma, are innately resistant to retinoid therapy." (PMID 28187790, 2017). "It has been shown that MYCN may act as a tumor-associated antigen, since MYCN-specific cytotoxic T-cells were detected in MYCN-amplified neuroblastoma patients." (PMID 28358317, 2017). "Similarly, ATRX mutations, TERT rearrangements and MYCN amplification define mutually exclusive molecular subgroups of neuroblastoma, all of which are associated with poor prognosis." (PMID 29340109, 2017). "The reports that high MYCN is associated with enhanced tumor angiogenesis and poor clinical outcome in neuroblastoma and the known antiangiogenic activity of SF1126 prompted us to explore a possible effect of SF1126 on the microvasculature of these NB9464 neuroblastomas." (PMID 28881723, 2017). "Finally, ALK mutations and MYCN amplification co-occur in a subset of neuroblastoma patients, emphasizing the need to target both oncogenes." (PMID 28425916, 2017). "Besides amplification of the MYCN oncogene (in approximately 20% of neuroblastomas), ALK mutations and amplifications occur in 9% and 2-3%, respectively." (PMID 29221117, 2017). "High-risk neuroblastoma (HR-NB) has long included MYCN-amplified stage 2 or 3 disease." (PMID 29221128, 2017). "Multiple epidemiological studies on the distribution of ALK mutations in relation to MYCN status and other genomic parameters have revealed the co-occurrence of ALK mutations and MYCN amplification in neuroblastoma, indicating that additional oncogenic drivers exist other than ALK." (PMID 28425916, 2017). "The main finding in this analysis is that on average, integrin αvβ3 was expressed on 68% (95% CI 57%–79%; n = 17) of microvessels in stage 3 MYCN-amplified (high risk) neuroblastomas, but only on 34% (95% CI 26%–42%, n = 34, p < 0.001) of microvessels in MYCN-non-amplified ones." (PMID 28881723, 2017).
neuroblastoma (continued). "Furthermore, we recapitulate a number of compounds targeting proteins associated to neuroblastoma: MYCN (direct and indirect inhibitors) and downstream targets, Trk, ALK and its downstream signalling pathways." (PMID 28178969, 2017). "Moreover, CHERP expression was associated with patient age, cause of death and stages and MYCN status of neuroblastoma patients." (PMID 29113358, 2017). "In addition, ceritinib and CGM097 combination overcomes acquired ceritinib resistance caused by MYCN upregulation in an ALK-driven neuroblastoma model." (PMID 28425916, 2017). "Kurihara and colleagues analyzed plasma-derived cfDNA from patients with a variety of childhood solid tumors before and after surgery using next-generation sequencing and ddPCR for mutations, deletions or amplifications, including MYCN status in neuroblastomas." (PMID 29156716, 2017). "Amplification of the MYCN gene occurs in 40-50% of the high risk neuroblastoma." (PMID 29088756, 2017). "Therefore, it is likely that both mitotic arrest and loss of p4E-BP1-mediated cap-dependent protein translation contribute to the loss of MCL-1 following MLN8237 treatment in MYCN-amplified neuroblastoma cells." (PMID 26859456, 2016). "By contrast, the highest neuroblastoma penetrance levels at 4 weeks of age (82.6%) was observed in MYCN transgenic fish with homozygous loss of nf1a and heterozygous loss of nf1b, which produced the earliest onset and highest penetrance of neuroblastoma that we have observed in this model system." (PMID 27130733, 2016). "Additionally, MYCN amplified (MNA) neuroblastoma cells were preferentially susceptible to Wnt activation." (PMID 27531891, 2016). "A particular region of the CpG island encompassing CASR gene promoter 2 was found to be hypermethylated in 25% primary neuroblastomas, in association with reduced CaSR mRNA expression, MYCN amplification, undifferentiated histopathology and other factors of poor outcome." (PMID 27242543, 2016). "Furthermore, loss of heterozygosis (LOH) at chromosome 10 is found exclusively at 10p11.23–p15.1 and consequently associated with MYCN-amplified Stage IV tumors in neuroblastoma tumors." (PMID 27064200, 2016). "The activity of inhibitors of MYCN in high-risk neuroblastoma may partly result from inhibition of mitochondrial based metabolism." (PMID 27821095, 2016). "Amplification or overexpression of MYCN is associated with poor prognosis of human neuroblastoma." (PMID 27571165, 2016). "Therefore, in MYCN-amplified neuroblastoma, MLN8237 inhibits p4E-BP1, leading to loss of eIF4G:eIF4E complex-mediated MCL-1 protein translation." (PMID 26859456, 2016). "We did not detect significant differences in mRNA levels of these genes, suggesting that further experiments are required to decipher the molecular mechanism through which the loss of nf1a promotes increased proliferation of MYCN-overexpressing neuroblastoma tumor cells." (PMID 27130733, 2016). "Neuroblastomas can be detected in most MYCN-transgenic fish with nf1a loss by 3 weeks of age, when the fish are very small, making it feasible to test the effectiveness of many drugs and drug combinations for their ability to kill primary neuroblastoma cells in vivo." (PMID 27130733, 2016). "miRNAs have been implicated in neuroblastoma metastasis, MYCN regulation, and cell differentiation; thus they may serve as novel therapeutic targets, especially in high-risk, MYCN-amplified patients." (PMID 28035989, 2016). "The most relevant factors associated with these different clinical behaviors of neuroblastomas are age at diagnosis, clinical stage, MYCN amplification, alterations of ploidy, numerical and structural chromosomal abnormalities, and histological degree of differentiation." (PMID 27242543, 2016).
neuroblastoma (continued). "High-risk neuroblastoma is characterized by tumor cell dissemination into the bone marrow, organ metastasis, amplification of the MYCN oncogene (in 40% of cases, personal communication Ladenstein R. and Pötschger U.)and recurrent segmental chromosomal aberrations." (PMID 26657295, 2016). "Because very aggressive growth properties of MYCN-induced neuroblastomas in zebrafish with loss of both alleles of nf1a are attributable to aberrant activation of RAS-MAPK signaling, we evaluated the importance of MEK inhibition for the treatment of these tumors." (PMID 27130733, 2016). "We assembled a panel of neuroblastoma cell lines harboring mutated or wild-type ALK as follows: CLB-GE (amplified MYCN/ALK, ALKF1174V), CLB-BAR (amplified MYCN/ALK, ALK Δexon 4-11), IMR32 (ALK exon 2-4 amplified ALK), CLB-PE (amplified MYCN) and SK-N-AS (non-amplified MYCN, WT ALK)." (PMID 27483357, 2016). "Taking advantage of the optical transparency of our zebrafish neuroblastoma model, which allows us to monitor fluorescent tumor cell progression in vivo, we further investigated the compound effects of loss of nf1 and gain of MYCN on the kinetics of neuroblastoma progression." (PMID 27130733, 2016). "Few recurrent genetic events have been linked to neuroblastoma including tumour-specific amplification of the MYCN oncogene or mutations in the genes coding for anaplastic-lymphoma kinase (ALK) and the alpha thalassemia/mental retardation syndrome X-linked (ATRX) gene." (PMID 27716771, 2016). "Because of the very high penetrance and rapid onset of neuroblastoma in our nf1-deficient, MYCN-transgenic zebrafish model, it becomes one of a very few systems in which extensive analysis of the synergistic activity of two or more drugs can be evaluated in primary tumors in vivo." (PMID 27130733, 2016). "Finally, neuroblastomas with high levels of MYCN expression exhibit defined metabolic deficiencies in glucose metabolism (Warburg physiology) and are polyamine-dependent under hypoxic conditions." (PMID 27438153, 2016). "Importantly, in a transgenic mouse model of neuroblastoma (TH-MYCN) that overexpresses MYCN protein and is predisposed to spontaneous neuroblastoma formation, this compound significantly inhibits tumor growth." (PMID 26734566, 2015). "In addition, these genes were predicted to be under the transcriptional control of MYCN/MYC regulatory network making them potential therapeutic targets in high-risk neuroblastoma." (PMID 26497213, 2015). "Mutation of the ALK tyrosine kinase receptor occurs together with MYCN amplification in a subset of human neuroblastomas and may be one such tumor-promoting mutation." (PMID 26222553, 2015). "and since c-MYC and MYCN proteins share extensive structural and functional similarities we sought to determine whether LSD1 and MYCN can be associated in Neuroblastoma cells where MYCN is critical to the oncogenic process." (PMID 26062444, 2015). "MYCN is known to be amplified in 16-25% of neuroblastomas, an aberration associated with a poorer prognosis, and it undergoes prognostically relevant copy number gain, and more rarely amplification, in other paediatric tumours including medulloblastoma and rhabdomyosarcoma." (PMID 25749049, 2015). "MYCN has a causative role in Neuroblastoma and its amplification correlates with poor prognosis." (PMID 26062444, 2015).
neuroblastoma (continued). "The compounds, either alone or in combination, caused death in the majority of MYCN-amplified cells, suggesting that clinically viable derivatives of these compounds could be used to treat high risk neuroblastomas and other tumors driven by MYC." (PMID 25477524, 2015). "In the current study we demonstrate that baseline R2* and hyperoxia-induced ΔR2* can discriminate a differential hemodynamic tumor vascular phenotype between tumors arising in Th-ALKF1174L/Th-MYCN and Th-MYCN models of high-risk, MYCN over-expressing neuroblastoma." (PMID 24667968, 2014). "This supports the idea that therapies that interfere with MYCN function may have significant therapeutic value in high-risk neuroblastoma." (PMID 24759734, 2014). "A factor that is strongly associated with advanced high-risk neuroblastoma and predicts poor outcome is amplification and concomitant high expression of MYCN, an oncogene encoding N-Myc, a nuclear phosphoprotein in the Myc family of helix-loop-helix transcription factors." (PMID 25277194, 2014). "The altered vascular phenotype may also impact on the response to anti-vascular therapies, including cediranib, currently being considered in clinical trials for the treatment of high-risk MYCN-amplified neuroblastoma." (PMID 24667968, 2014). "The alterations in karyotype and cytogenetic characteristics, such as genomic amplification of MYCN gene, mutations in tumor suppressor genes and rearrangement or deletion in chromosomes, develop drug resistance and help neuroblastoma tumors to escape most available therapies." (PMID 25365944, 2014). "Here we show that NCYM, a cis-antisense gene of the MYCN oncogene, initially thought to be a large non-coding RNA, encodes a de novo evolved protein regulating the pathogenesis of human cancers, particularly neuroblastoma." (PMID 24391509, 2014). "Accordingly, two small-molecule antagonists of MDM2, Nutlin-3, and MI-63, might be of particular interest in treating MYCN-dependent diseases, such as high-risk neuroblastoma." (PMID 24515800, 2014). "Intrinsic susceptibility-MRI could thus potentially provide a non-invasive and clinically-exploitable method to help identifying children with MYCN-driven neuroblastoma harboring the ALKF1174L mutation at the time of diagnosis." (PMID 24667968, 2014). "Given the potential therapeutic benefit of MYC-family transcription factor inhibition in a wide variety of cancers, we investigated the effects of BET inhibition in neuroblastoma, an aggressive pediatric cancer associated with a high frequency of MYCN gene amplification." (PMID 24009722, 2013). "MYCN (or N-Myc) is a proto-oncogene that normally encodes a transcription factor involved in regulating cell cycle progression, apoptosis, cell proliferation and neurogenesis and it is overexpressed in neuroblastoma, medulloblastoma, and Wilm’s tumor." (PMID 24202319, 2013). "Age at diagnosis, stage and amplification of the N-myc proto-oncogene (MYCN) are clinical and molecular risk factors that the International Neuroblastoma Risk Group (INRG) utilized to classify patients into high, intermediate and low risk subgroups on which current therapeutic strategy is based." (PMID 23815266, 2013). "MYCN is a proto-oncogene implicated to be directly involved in neuroblastoma development." (PMID 23226679, 2012). "Interestingly, miR-34a is located at 1p36.23, a region showing frequent loss of heterozygosity (LOH) in neuroblastoma and which is associated with MYCN amplification and aggressive disease progression." (PMID 23226679, 2012). "However, in neuroblastoma the generation of multiple copies of the MYCN gene causes accumulation of the MycN oncoprotein, which binds to the B-MYB locus and activates its unregulated expression." (PMID 22619121, 2012).
neuroblastoma (continued). "Therapeutic approaches targeting the polyamine pathway may therefore provide an effective strategy for the treatment of high risk neuroblastoma, particularly in tumors dependent on deregulated Myc activity, such as those with MYCN amplification." (PMID 23181218, 2012). "These splicing regulators may be involved in MYCN-associated splicing regulation, through which MYCN may exert part of its phenotypic effects on neuroblastoma." (PMID 21501490, 2011). "The search for a miRNA expression signature associated with patient outcome was first performed on a preliminary cohort of 13 primary neuroblastoma tumours whose risk at diagnosis was defined according to clinical criteria (age at diagnosis and stage) and MYCN amplification." (PMID 21970883, 2011). "In this same journal, the International Neuroblastoma Risk Group (INRG) Biology Subcommittee recommends fluorescence in situ hybridisation (FISH) to establish the MYCN status, whereas segmental aberrations are currently detected using either FISH or polymerase chain reaction." (PMID 21654680, 2011). "Thus, our study clearly shows the clinical potential of miR-410 and miR-487b for the non-MYCN-amplified low-risk neuroblastoma." (PMID 21970883, 2011). "Moreover, miR-487b and miR-410 expression was significantly associated with disease-free survival of the non-MYCN-amplified favourable neuroblastoma: localised (stage 1, 2 and 3) and stage 4 of infant <18 months." (PMID 21970883, 2011). "Deregulated MYCN expression is a hallmark in high-risk neuroblastoma." (PMID 21654684, 2011). "MYCN-amplification is associated with the most aggressive phenotype of neuroblastoma." (PMID 22132187, 2011). "One likely scenario is that in tumours of the nervous system like neuroblastoma, the generation of multiple copies of the MYCN gene in DM bodies or HSRs chromosomes causes accumulation of the MYCN oncoprotein which binds to the B-MYB locus, activating its unregulated expression." (PMID 21304178, 2010). "In summary, these findings suggest that MYCN binding occurs more commonly at CATGTG as opposed to the classic CACGTG E-box motif, and that disease associated over expression of MYCN leads to aberrant binding to additional weaker affinity E-box motifs in neuroblastoma." (PMID 19997598, 2009). "Although numerous genetic abnormalities, including MYCN amplification, are associated with tumour progression and poor outcome, the molecular mechanisms responsible for the pathogenesis of aggressive neuroblastoma remain unclear." (PMID 19165202, 2009). "In this study, we asked whether distinct transcriptional MYCN or c-MYC activities are associated with specific neuroblastoma phenotypes." (PMID 18851746, 2008). "Our data show that markers of increased MYCN/c-MYC activity are consistently represented in these classifier gene lists, indicating that a gene expression-based classifier that reflects MYCN/c-MYC function should make an attractive tool for neuroblastoma classification and risk prediction." (PMID 18851746, 2008). "The neuroblastoma progression linked to MYCN amplification, although well documented, is mediated by unknown molecular mechanisms." (PMID 18493594, 2008). "MYCN amplification, 1p-loss and 17q gain are strongly associated with aggressive tumour and unfavourable outcome for the patient, whereas triploidy is associated with low stage neuroblastomas and a favourable outcome." (PMID 16359544, 2005). "In addition, these noninvasive imaging biomarkers may have potential for characterizing MYCN amplification status and for exploring risk stratification in neuroblastoma." (PMID 41228227, 2025). "It is worth mentioning that such a chromosomal reintegration may only be relevant if it confers fitness to the cells and results in clonal selection as demonstrated in neuroblastoma, where MYCN ecDNA clustered reintegration is associated with worse patient survival." (PMID 39748050, 2025).